SATB1 (SATB homeobox 1)
Diseases named in the same sentence as SATB1 in open-access papers (continued):
Sharing a sentence is not in itself a finding about the gene and the disease.
tumor (continued). "In vivo, systemic treatment of tumor xenograft-bearing mice with siRNAs formulated in polymeric nanoparticles inhibits tumor growth of two HNSCC xenograft models, resulting from therapeutic SATB1 reduction and concomitant decrease of proliferation and induction of apoptosis." (PMID 32451408, 2020). "On the other hand, in some studies SATB1′s expression lacked a prognostic value or was a prognostic factor only in SATB2-negative tumours." (PMID 31450715, 2019). "Furthermore, SATB1′s expression positively correlated with the depth of invasion, the TNM stage of the tumour and the presence of lymph nodes and distant metastasis." (PMID 31450715, 2019). "Similarly, in an experiment using the gain-of-function model, ectopic SATB1′s overexpression in SW480 cells injected into mice resulted in a faster growth rate and an increase in the weight of the tumours compared to the control." (PMID 31450715, 2019). "MiR-302a-3p and miR-3130-3p restrained tumor progression by decreasing expression of downstream gene NFYA, which could have acted as a transcriptional factor for SATB1." (PMID 29467441, 2018). "Apart from the discoveries of these physiological roles, considerable studies have been focused on SATB1, given its vital role in gastric cancer, breast cancer, and CRC, which suggest its critical role in promoting tumor invasion and metastasis." (PMID 29867574, 2018). "We found that SATB1 and HES6 expressed higher in tumor tissues than in peritumor cells." (PMID 29050307, 2017). "SATB1 has also been proposed as an important factor that controls the development and progression of various human neoplasms; however, its role in cancer pathogenesis has yet not been fully elucidated." (PMID 25874491, 2015). "Nevertheless, the detailed mechanisms by which SATB1 promotes tumor invasion and metastasis are not completely understood." (PMID 25762622, 2015). "The relative SATB1 mRNA level did not correlate with patients’ sex, age, tumor localization, TNM disease stage, depth of invasion, lymph node involvement, and the presence of metastases." (PMID 25874491, 2015). "Our finding of higher SATB1 nuclear immunoreactivity in CRC tumor than in the matched noncancerous mucosa is in line with the results of other authors, although there are differences in the percentage of immunopositive tissues." (PMID 25874491, 2015). "SATB1 protein levels, nuclear as well as cytoplasmic immunoreactivity did not correlate with patients’ sex, age, tumor localization, TNM disease stage, depth of invasion, lymph node involvement, and the presence of metastases." (PMID 25874491, 2015). "SATB1 expression was not significantly correlated with other clinicopathological features including tumor site, tumor size, and lymph node metastasis." (PMID 24971456, 2014). "SATB1 expression was not different between primary tumors and metastases, indicating that it is sufficient to examine only the primary tumor for prognostic purposes." (PMID 25326863, 2014). "Out of the 11 cases with positive SATB1 expression in a metastasis, 6 (54.5%) had positive and 5 (45.5%) had negative SATB1 expression in the corresponding primary tumour." (PMID 25323550, 2014). "In contrast to the PB-group, SATB1 expression was not prognostic for OS or RFS in the I-type category of tumours." (PMID 25323550, 2014). "Among the 21 matched cases, SATB1 mRNA and protein were detected in 17 tumor samples but not in any of the non-tumor mucosa samples." (PMID 24971456, 2014). "When combining positivity in primary tumours and/or metastases, there were 16 (25.4%) SATB1 positive and 47 (74.6%) negative I-type cases." (PMID 25323550, 2014). "Moreover, SATB1 and CCND2 repression by miR-191 are related to the suppression of the PI3K/AKT pathway and the corresponding reduced cell proliferation and tumor growth." (PMID 23505378, 2013).
tumor (continued). "We injected SATB1-overexpressing MCF10A-1 cells (pooled pLXSN-SATB1 and single cell-derived clone-1) or vector control cells into the fat pad of the fourth mammary gland and monitored tumor formation." (PMID 23251624, 2012). "However, the expression of SATB1, a close homologue of SATB2, is significantly upregulated in most of these tumor samples." (PMID 22815795, 2012). "In the evaluated CRC cohort, 307 (58.0%) of the tumours were SATB1 negative, and in the remaining tumours, SATB1 was expressed in various fractions and intensities." (PMID 22935204, 2012). "The association between SATB1 expression and adverse outcome in SATB2 negative tumours is of potential significance, although based on a post-hoc analysis in a rather small subgroup." (PMID 22935204, 2012). "have discovered that SATB1 protein is expressed in poorly differentiated infiltrating tumor, but is absent in normal tissue." (PMID 22839214, 2012). "Such selectivity for SATB1 activity suggests that reduced ATM level serves as a molecular determinant for SATB1 tumor-inducing activity in non-malignant cells." (PMID 23251624, 2012). "Three categories of staining were compared, i.e. SATB1 negative tumours (NS = 0), an intermediate group (NS = 1-3), and SATB1 high tumours (NS > 3)." (PMID 22935204, 2012). "SATB1 expression was not prognostic in low-grade tumours or in subgroups according to histological type (data not shown)." (PMID 22992394, 2012). "Additionally, within TME, TGF-β-mediated SATB1 silencing promotes follicular helper T (Tfh) cell differentiation and tertiary lymphoid structures (TLS) formation, further underscoring its multifaceted role in immune regulation and tumor immunity." (PMID 41372119, 2025). "Therefore, we hypothesized that there may be a crucial regulatory relationship between SATB1 and MMP-9 and EMT during the formation of tumor growth, metastasis and chemoradioresistance in NPC." (PMID 33390772, 2021). "Since a previous study had demonstrated SATB1 expression by stroma, we employed immunohistochemical staining for the determination of SATB1 expression in the tumor tissues rather than the determination of SATB1 levels from tumor lysates." (PMID 33572976, 2021). "Of note, one-way ANOVA and Bonferroni's post hoc test of immune response and hypoxia-inducible indicators showed that the percentage of HIF1α and density of CD8+ and CD8+SATB1+ were significantly higher in stroma than in the tumor compartment (p < 0.0001) (data not shown)." (PMID 32612954, 2020). "The somewhat contradictory findings published in the literature and in databases regarding SATB1 overexpression in solid tumors may also indicate that expression levels might not be the most important parameter for defining its (tumor-)biological relevance." (PMID 32451408, 2020). "Moreover, modifying SATB1′s expression did not alter the anchorage-independent cell proliferation and migration ability in cultured cells, and it did not affect tumour formation and metastasis in xenograft mouse models." (PMID 31450715, 2019). "Additionally, SATB1′s expression correlated with TNM stage and the tumours’ invasion depth." (PMID 31450715, 2019). "Notably, in comparison to normal brain tissue no SATB1 upregulation was observed in tumors, with tumor levels rather being even lower (left)." (PMID 28049521, 2017). "Notably, SATB1 protein expression in tumor nuclei needs to be carefully evaluated to assess its correlation with tumor characteristics and not whole mRNA levels due to SATB1 expression in stromal cells (e.g., lymphocytes) as well." (PMID 28636989, 2017). "Doxorubicin (DOX) and SATB1 shRNA vector were loaded into the co-delivery system, and in vitro DOX thermosensitive release activity, targeted gene silencing efficiency, targeted cellular uptake, in vitro cytotoxicity, as well as in vivo anti-tumor activity were determined." (PMID 24675979, 2014).
tumor (continued). "This not only validates the use of the cohort for biomarker studies but also strengthens the prognostic value of SATB1 expression in radically resected tumors, in particular since an earlier study was limited by a lack of information on residual tumor after surgery." (PMID 25326863, 2014). "This may be due to differences in experimental design, e.g., examining SATB1 expression in total RNA transcripts from tumor tissue specimens as opposed to scoring SATB1 protein levels in individual tumor cells by immunohistochemistry." (PMID 25326863, 2014). "Another explanation could be that SATB1 and SATB2 exert synergistic effects in the majority of CRC, as reflected in their positive interrelationship, but that, in the absence of SATB2, SATB1 may reprogramme the tumours towards a more malignant phenotype." (PMID 22935204, 2012). "Whereas earlier studies examined SATB1's role in the progression of tumor cells, here we took a more direct approach and asked whether forced expression of SATB1 in non-malignant breast epithelial cells could induce a malignant phenotype." (PMID 23251624, 2012). "Furthermore, while not prognostic in unstratified analysis, SATB1 expression is shown to be a factor of poor prognosis in SATB2 negative tumours." (PMID 22935204, 2012). "SATB1 is the best characterized MAR-binding protein, and its roles in the higher order of chromatin loop organization and global transcriptional regulation have been widely documented; however, data on its expression level and its role in tumor development are still conflicting." (PMID 22808207, 2012). "Furthermore, while not prognostic in the full cohort, SATB1 expression was found to be a factor of poor prognosis in SATB2 negative tumours." (PMID 22935204, 2012). "Interestingly, even a modest reduction in the SATB1 level (70%) abrogated lung metastasis, with no major reduction in tumor formation." (PMID 23251624, 2012). "Moreover, SATB1 expression was positively correlated with the Gleason score, though it did not correlate with patient age or prostate-specific antigen levels, indicating its role in tumor progression rather than early detection." (PMID 40071088, 2025). "Subsequent studies have consistently confirmed that SATB1 is overexpressed in CRC samples relative to adjacent non-malignant tissues, with its overexpression associated with deeper tumor infiltration, lymph node metastasis, poor differentiation, and advanced TNM stages." (PMID 40071088, 2025). "Furthermore, SATB2 closely related gene SATB1 did not affect tumor development." (PMID 33527896, 2021). "Based on this, one can also conclude that SATB1 inhibition in normal cells may not necessarily lead to (unwanted) effects in these cells similar to the desired effects in tumor cells, since this may well rely on the levels of genes affected by SATB1 and its inhibition." (PMID 32451408, 2020). "Since previously direct effects of SATB1 on HER2 have been shown, one explanation for this discrepancy may be mutual effects of one HER receptor (here: EGFR) on the expression of other family members (here: HER2), as found in other tumor entities (Gutsch and Aigner, unpublished)." (PMID 28049521, 2017). "Furthermore, SATB1 expression is a factor of poor prognosis in SATB2 negative tumours." (PMID 22935204, 2012). "Notably, none of the SATB2 negative tumours displayed high SATB1 staining." (PMID 22935204, 2012). "SATB1 has been shown previously in other tumor entities to influence the expression of HER receptor family members which were sometimes, but not always, found affected by SATB1 overexpression or inhibition (15,29,30; see17 for review)." (PMID 32451408, 2020). "No relevance was observed between the expression of SATB1, HER2 or HR with age, tumor size, tumor type, lymph node status and TNM stage (p > 0.05 for each)." (PMID 25956130, 2015).
tumor (continued). "This is a novel observation since SATB1 expression has not previously been studied in normal colon mucosa of healthy individuals, although it was determined in CRC tumor tissue." (PMID 25874491, 2015). "SATB1 expression was positive in 2 and negative in 1 of the 3 cases with SATB2-positive PB-type tumours." (PMID 25323550, 2014). "While previous studies have already suggested SATB1 as putative prognostic marker in HNSCC19–21, the analysis of its functional role so far rested on a very few cell lines, thus not addressing possible intra- and inter-tumor heterogeneity." (PMID 32451408, 2020). "In the present study, the level of SATB1 expression in CRC tissues did not correlate with patients’ sex, age, tumor localization, TNM disease stage, depth of invasion, lymph node involvement, and the presence of metastases; furthermore, it had no impact on patients’ overall survival." (PMID 25874491, 2015).
cancer (106 papers, 2010 to 2025). A tumor composed of atypical neoplastic, often pleomorphic cells that invade other tissues. "BLCA is ranked as the sixth most common cancer in men worldwide, and it has also been linked to SATB1 overexpression." (PMID 40071088, 2025). "SMURF2, another E3 ubiquitin ligase, promotes SATB1 degradation by upregulating its ubiquitination, and its deficiency promotes cancer cell proliferation and SATB1 target gene transcription." (PMID 40071088, 2025). "Special AT-rich sequence-binding protein 1 (Satb1) derived cancer-associated dendritic cells (DCs) differentiation by activating NOTCH1 signaling to regulate major histocompatibility complex class II (MHC II) expression." (PMID 37386521, 2023). "Special AT-rich binding protein 1 (SATB1), a poorly understood transcription factor implicated in cancers such as breast and gastric, is directly regulated by LMP1 in EBV infected epithelial cells." (PMID 35804891, 2022). "This was because the SATB1-gene interaction network generated by FunRich software suggested that SATB1 was closely associated with other cancer-correlated genes, such as GATA3, HDAC1, and MTA2." (PMID 34604093, 2021). "In numerous loss-of-function models the expression of SATB1 was shown to be essential to maintain the invasive phenotype of cancer cells and their high proliferation rate." (PMID 31450715, 2019). "SATB1 is well-known for its ability to regulate the expression of as many as 1000 genes associated with cancer development and progression, and HER-2/neu appears to be one of these genes." (PMID 31737131, 2019). "The specific function of SATB1 still remains not fully known, especially in the context of mechanisms underlying the development of malignant phenotype of cancer cells." (PMID 31737131, 2019). "The association of SATB1 was also observed in several other cancers, including colorectal cancer, prostate cancer, endometriod endometrial cancer, liver cancer, rectal cancer, bladder cancer, ovarian cancer and gastric cancer." (PMID 28147311, 2017). "RFS was only reported in five studies and the combined HR was 2.46 (95% CI 1.87–3.24, p < 0.0001), which indicated that SATB1 overexpression is associated with 2.46 fold increased risk of cancer relapse in gastrointestinal tract cancer." (PMID 28430598, 2017). "The cooperative regulation of the BCL2 and NOXA genes by SATB1 at higher-order chromatin structure levels is significant in view of the profound association of SATB1 with cancer development and chemotherapy resistance." (PMID 26422397, 2015). "Aberrant expression of special AT-rich binding protein 1 (SATB1), a global genomic organizer, has been associated with various cancers, which raises the question of how higher-order chromatin structure contributes to carcinogenesis." (PMID 26422397, 2015). "In recent years, aberrant expression of SATB1 has been associated with various cancers, including breast, hepatocellular, prostate and others." (PMID 26422397, 2015). "SATB1 has subsequently been found to be aberrantly expressed in several malignant tumors, where its expression is associated with various clinicopathologic factors." (PMID 23326301, 2013). "Important functions for SATB1 have been implicated in several other cancer forms, and its prognostic value seems to be cancer-type specific." (PMID 22935204, 2012). "The increased expression of SATB1 correlates with expression profiles of various epigenetic factors including KDM6A, KDM6B and EMT factors Snail and ZEB1 suggesting a crosstalk between various EMT factors, SATB1 and epigenetic factors which drives the cancer towards metastasis associated." (PMID 40071088, 2025). "SATB1 is associated with cancer cell proliferation, migration, and invasion." (PMID 35027621, 2022). "SATB1 is associated with drug resistance in several cancers." (PMID 33390772, 2021).